ICOS (inducible T cell costimulator)
Diseases named in the same sentence as ICOS in open-access papers (continued):
Sharing a sentence is not in itself a finding about the gene and the disease.
Autoimmunity (continued). "ICOS is a co-stimulatory molecule expressed by activated T cells with an important but complex role in the induction of T cell anergy in vitro and the development of autoimmunity in vivo." (PMID 31266507, 2019). "ICOS deficiency should be ruled out in patients in whom immunodeficiency and autoimmunity or immune dysregulation coincide." (PMID 28861081, 2017). "Several observations hint toward a role of ICOS-mediated signaling in autoimmunity." (PMID 28861081, 2017). "Similarly, antagonizing B7RP1 may be safer because targeting at ICOS may actually stimulate it and potentially triggers more severe autoimmunity." (PMID 24000287, 2013). "T follicular regulatory (Tfr) cells are a subset of FOXP3 Treg cells that also express PD-1, ICOS, CXCR5, CD25, Bcl-6, and Foxp3 and suppress Tfh–B cell interactions to limit autoimmunity." (PMID 32973682, 2020). "A striking observation in ICOSL−/−, as well as in ICOS−/− NOD mice, is the deviation of autoimmunity from the islets toward muscles and peripheral nerves." (PMID 28424681, 2017). "More specifically, CD5hi human Treg preferentially express ICOS, FOXP3, GITR, and CTLA4 similar to a subpopulation of these cells in mice that are more protective in the context of tissue‐specific autoimmunity and immune homeostasis as compared to their CD5lo counterparts." (PMID 33682083, 2021). "Altogether, the deviation of autoimmunity from the pancreas to skeletal muscles in the absence of ICOS/ICOSL signaling in NOD mice is strictly dependent on CD4+ T-cells, leads to myofiber necrosis and regeneration." (PMID 28424681, 2017). "Nevertheless, we did not observe increasing frequencies of PD-1+ or ICOS+ cTfh cells as it has been previously observed in ab-mediated autoimmunity suggesting that in pemphigus the relative number of total cTfh is altered." (PMID 26872212, 2016). "Indeed, patients with ICI-T1DM had a more robust Tfh cell response than those without IrAEs, with increased CD4+ICOS+PD-1hiCXCR5+ cells compared with controls without autoimmunity (P < 0.05)." (PMID 40626363, 2025). "Treg function is modulated by the costimulatory molecules, like inducible costimulator (ICOS) that are crucial in orienting T cell differentiation and function so that they strongly impact on the immunologic decision between tolerance or autoimmunity development." (PMID 35664973, 2021). "The combined use of CTLA4Ig and anti‐ICOS mAb in our model was far superior in blocking primary CD4+ T‐cell responses, suggesting this dual targeting may have significantly enhanced clinical benefit in treating autoimmunity and graft rejection." (PMID 25754933, 2015). "The positive regulatory co-receptors CD28 and inducible co-stimulator (ICOS) transduce stimulatory co-signals, whereas the negative regulatory co-stimulators CTLA-4 and PD-1 are critical for the regulation of peripheral tolerance and autoimmunity." (PMID 28770269, 2018). "However, no overt autoimmunity was noted and the reduction in CD4 ICOS levels does not support ongoing T cell activation." (PMID 28646160, 2017).
influenza (34 papers, 2011 to 2025). An acute viral infection of the respiratory tract, occurring in isolated cases, in epidemics, or in pandemics; it is caused by serologically different strains of viruses (influenzaviruses) designated A, B, and C, has a 3-day incubation period, and usually lasts for 3 to 10 days. "The ability of a vaccine to activate cTfh cells is proportional to the subsequent protective antibody response, with increased expression of ICOS on cTfh cells associated with influenza-specific antibody production." (PMID 37063867, 2023). "In any case, these findings provide evidence that both TFH1 ICOS+ and antigen-specific CD4+IL-21+ICOS+CXCR5+ TFH cell subsets are associated with functional antibody responses to influenza vaccination." (PMID 27336786, 2016). "ICOS−/− mice developed significantly fewer influenza-specific EM CD4 T cells and were more susceptible to re-infection than wild-type mice." (PMID 21364749, 2011). "The association of ICOS expression on pTfh cells and vaccine responses has been established in several recent studies using bulk pTfh cells with varying phenotypes in healthy adults for influenza vaccine as well as in 3 different human HIV vaccine trials." (PMID 31100059, 2019). "Here it is revealed that the costimulatory receptors CD27 and ICOS coordinately sustain PD-1high CD8+ TRM cell populations following resolution of acute influenza infection." (PMID 41262009, 2025). "This is consistent with other studies, such as influenza vaccination which has been shown to elicit an increase of ICOS+ PD-1+ CCR7lo cTFH1 which positively correlated with the generation of protective antibody responses." (PMID 39328410, 2024). "Several studies show that the induction of ICOS+cTfh or IL-21+ICOS+cTfh cells in blood is correlated with heightened antigen-specific antibody titer or humoral immune responses to influenza vaccination in healthy cohorts or in HIV-1-infected patients." (PMID 35222430, 2022). "Our data found that expansion and IL-10 production by tissue resident Treg cells during influenza infection was counter-regulated by ICOS and PD-1 signaling." (PMID 36159872, 2022). "Blockade of PD-1 or ICOS signaling reveals that PD-1 and ICOS signaling pathways counter-regulate TR-Treg cell expansion and IL-10 production, during secondary influenza infection." (PMID 36159872, 2022). "The PD-1+ICOS+ cells represent the population of Tfh cells that transiently increases in circulation shortly after immune stimulation, such as that provided by influenza vaccination." (PMID 36271118, 2022). "In healthy adults, influenza vaccination induces a transient increase of circulating TFH cells that express activation markers ICOS and PD-115." (PMID 33594050, 2021). "Multiple studies have demonstrated the emergence of a transient population of PD-1+ICOS+ c-Tfh cells following vaccination with inactivated influenza vaccine." (PMID 33198297, 2020). "Strikingly, hybrid Th1/Tfh cells (ICOS+CXCR3+CXCR5+) did correlate with antibody levels in influenza, where they were also shown to contain IFN-γ+IL-21+ T cells." (PMID 32634740, 2020). "Among them, ICOS+ peripheral Tfh cells play a central role in the generation of antibody responses after influenza vaccination, likely before they exit the lymphoid organs." (PMID 33253297, 2020). "Consistent with such a role in influenza vaccination, we showed the emergence of circulating ICOS+ memory hu-Tfh cells in vaccinated hu-mice that significantly correlated with the magnitude of the Env-specific hu-B cell responses elicited by the vaccine." (PMID 33253297, 2020). "Compared with naïve mice, ICOS expression was downregulated during influenza infection, particularly at day 4 after inoculation." (PMID 29762870, 2019). "This expansion of ICOS+CD38+CXCR5+PD-1+ cTfh cells correlated positively with the increase in influenza-specific antibodies 7 and 42 d after vaccination." (PMID 31175140, 2019).
influenza (continued). "In fact, a previous study using tetramer staining and activation-induced marker (AIM) assay demonstrated an expansion of the Ag.pTfh population post influenza vaccination, with co-expression of ICOS and CD38 and IL-21 production in young HCs." (PMID 31100059, 2019). "Similar increases in blood CXCR3+CXCR5+ICOS+ Tfh cells occurred 7 days after influenza vaccination and correlated with anti-influenza antibody and plasmablast production." (PMID 29904381, 2018). "A subset of circulating ICOS+CXCR3+CXCR5+ TFH cells was reported to play a crucial part in inducing antibody responses in seasonal influenza vaccine trials." (PMID 28533093, 2017). "Generation of ICOS+PD-1+CXCR3+ Tfh cells is important for the generation of protective antibody response in influenza vaccine, in particular for subjects who have few highly cross-reactive antigen-experienced B cells." (PMID 27231124, 2016). "We previously showed that antigen-specific blood CD4+IL-21+ICOS+ TH cells expand three weeks after influenza vaccination." (PMID 27336786, 2016). "We also found ICOS was greatly induced in the Tfh1-like subset at day 6 post-influenza vaccination, and that these cells also expressed PD1." (PMID 26333070, 2015). "Similarly, to probe the role of ICOS signaling, αICOSL was administered during primary influenza infection." (PMID 36159872, 2022). "In our work, high levels of ICOS expression is well aligned with lung tissue resident Treg cell expansion and IL-10 production during flu, suggesting that ICOShigh is a feasible marker for characterizing active lung tissue resident Treg cells in flu models." (PMID 36159872, 2022). "Similarly, a recent study showed that emergence of plasmablasts and ICOS+CXCR3+CXCR5+CD4+ T cells in blood peaked on day 7 after influenza vaccination." (PMID 30055570, 2018). "In HIV seronegative individuals, the emergence of blood ICOS+CXCR5+CXCR3+ TFH that are able to produce IL-21 correlated with influenza-specific B cell responses and blood ICOS+IL-21+ influenza-specific TFH expand after immunization and correlate to antibody responses." (PMID 28082992, 2016). "To further define the role of PD-1 and ICOS signaling pathways in lung tissue resident T cell expansion and IL-10 production during flu re-infection, we tested the effects of PD-1 and ICOS signaling blockades during secondary influenza infection (D respectively)." (PMID 36159872, 2022). "To determine whether the reduced population of EM CD4 T cells in ICOS−/− mice was associated with reduced protection to re-infection, we infected Balb/c and ICOS−/− mice with the influenza virus Hkx31, rested the mice for over 30 days, then challenged with the more lethal strain of influenza, PR8." (PMID 21364749, 2011). "Increased frequencies of ICOS+ cTfh‐1 and ICOS+CD38+ cTfh cells have also been correlated with higher immunoglobulin G antibody levels in separate studies of influenza and pneumococcal vaccination." (PMID 36825370, 2023). "Inactivated influenza vaccine-induced c-Tfh cells were phenotypically similar to their GC counterparts, expressing various activation markers, including PD-1, CD38, ICOS and Ki67." (PMID 33198297, 2020). "Similar to influenza vaccine, we found induction of PD1+ICOS+ Tfh1 subset after the first dose of the HPV vaccines, which peaked on D7." (PMID 26333070, 2015). "More recently it was demonstrated that TFH-like cells with partial phenotype of GC TFH (ICOS+, PD1+, IL-21+) can be found in the blood of humans after vaccination with MF59-adjuvanted influenza vaccine." (PMID 24755693, 2014). "FACS analysis revealed rapid induction of ICOS expression on CD4+ and CD8+ T cells early after influenza infection." (PMID 25029240, 2014). "after the first dose of BNT162b2 vaccination (and a slight increase upon second dose) among the cTfh cells (PD‐1+CXCR5+) that expressed ICOS+CD38+, wherein these activated cells have been correlated with antibody responses and overlapping clonality after successive influenza vaccinations." (PMID 36825370, 2023).
influenza (continued). "In agreement with these, compared to circulating Treg cells, we found that lung tissue resident Treg cells express higher levels of PD-1, TIGIT and GITR, even at the naïve state, while ICOS and LAG-3 are significantly upregulated following acute influenza infection." (PMID 36159872, 2022). "Knowledge of the role of ICOS and PD-1 signaling in lung tissue resident Treg cells is limited and has not been explored in the context of influenza infection." (PMID 36159872, 2022). "Here, we show that activated PD-1+ICOS+ cTfh1 cells emerged within influenza-infected patients in parallel with ASC responses, both peaking between days 7 and 10 after disease onset in both influenza+ and influenza- groups, prior to patients’ recovery." (PMID 33976217, 2021). "cTfh cells share phenotypic and functional properties to GC Tfh cells, and it has been shown that inactivated influenza vaccination (IIV) induces expansion and PD-1/ICOS-activation of CD4+CXCR5+CXCR3+ cTfh type-1 (cTfh1) cells, which correlated with antibody and CD19+CD27++CD38++ ASC responses." (PMID 33976217, 2021). "Germinal centers were formed in vaccine-draining lymph nodes along with an increase in circulating H10-specific ICOS+ PD-1+ CXCR3+ T follicular helper cells, a population shown to correlate with high avidity antibody responses after seasonal influenza vaccination in humans." (PMID 29181005, 2017). "However, in response to influenza vaccine, CXCR3+ Tfh1-like cells transiently expressed ICOS, along with PD1, which peaked on day 7 post-vaccination, and that these cells were able to provide help to memory B cells." (PMID 26333070, 2015). "While in this study ICOS deficiency resulted in a reduced Mtb-specific CD8+ T cell response, ICOS−/− mice displayed no defect in the initial pathogen-specific CD8+ T cell expansion or cytotoxic effector function following influenza A virus (IAV) infection." (PMID 25029240, 2014). "We first tested expression of these cell-surface receptors after seasonal influenza vaccination, a routine nonadjuvanted inoculation in which cTfh cell expansion has been well described and in which expression of ICOS and CD38 has been reported on cTfh cells." (PMID 31175140, 2019).
colorectal cancer (26 papers, 2017 to 2025). A primary or metastatic malignant neoplasm that affects the colon or rectum. "Tumor-associated m2 macrophages induced by Tregs and ICOS participate in the dynamic balance of the colorectal cancer tumor microenvironment, and their interaction affects colorectal carcinogenesis and progression." (PMID 39104717, 2024). "Conclusively, expression of ICOS is associated with improved survival in colorectal cancer." (PMID 33949771, 2021). "Additionally, a higher percentage of ICOS+ T cells in peripheral blood may serve as a marker for good prognosis in colorectal cancer, whereas lower ICOS expression is linked to a poorer prognosis in oral squamous cell carcinoma." (PMID 39201462, 2024). "Indeed, ICOS/CD4 correlation has been reported in colorectal cancer, where expression is associated with improved survival and may be a clinical biomarker for good prognosis." (PMID 32487090, 2020). "High expression of ICOS RNA was associated with high PD-1, high PD-L1, high CTLA-4, and non-colorectal cancers." (PMID 40297627, 2025). "In contrast, colorectal cancer patients rarely had high expression in ICOS and CD40 (RR: 0.30 and 0.40, respectively)." (PMID 37553332, 2023). "ICOS positivity on TILs in gastric and colorectal cancers is shown to impact negatively on survival, while in oesophageal adenocarcinoma, ICOS alone, and in the presence of CD45RO, was found to significantly improve 5 year OS." (PMID 37527282, 2023). "Further, PDL1 inhibition induces the expansion of CD4/CD8 T cells expressing ICOS molecules in the tumor microenvironment of colorectal cancer patients." (PMID 37261362, 2023). "In colorectal cancer, high ICOS expression by activated effector T cells was correlated with improved survival." (PMID 33803936, 2021). "Our results can also explain the positive correlation between higher ICOS expression and a better overall survival in colorectal cancer patients." (PMID 31412943, 2019). "Multivariate analysis demonstrated that high ICOS RNA levels were independently associated with patients not having colorectal cancer (p = 0.0009)." (PMID 40297627, 2025). "We show an association between HMGB1 expression intensity and density of immune cell subsets in colorectal cancer; nuclear and cytoplasmic HMBG1 associated with increased CD4+ lymphocytes, and nuclear HMGB1 associated with increased FOXP3+ and ICOS+ lymphocytes and reduced CD8+ T-cells." (PMID 36980751, 2023). "In summary, ARG1 was positively correlated with TIM3, TIGIT and ICOS in colorectal cancer." (PMID 38012650, 2023). "Low ICOSL was independently associated with not having colorectal cancer and with low ICOS." (PMID 40297627, 2025). "Hence, this detection of the TAI cells in human tumors could thus pave the path to clinically target these cells in colorectal cancer by e.g. combined PD-1/PD-L1 and ICOS targeted immunotherapy." (PMID 31412943, 2019). "We analyzed the immune cell infiltrates of head and neck squamous cell carcinoma and colorectal cancers and identified a subset of CD4+ Th cells distinct from FOXP3+ Tregs that coexpressed programmed cell death 1 (PD-1) and ICOS." (PMID 35439168, 2022). "CD4+ TAI subsets co-expressing inhibitory PD-1 and activating ICOS as well as CD39 and CD69 were detectable in freshly resected colon tumor from MMRd colorectal cancer patients known to express neo-epitopes due to accumulated point-mutations." (PMID 31412943, 2019). "This study, involving immunohistochemical (IHC) staining of cancerous, peritumoral, and normal tissues from 268 colorectal cancer (CRC) patients, has for the first time discovered a correlation between ICOS, M2 macrophages, and regulatory T cells (Tregs) in CRC." (PMID 39104717, 2024). "MiR21 can modulate ICOS-ICOSL expression and contribute to the progression of colorectal cancer." (PMID 28637496, 2017).
colorectal cancer (continued). "High ICOS (⩾75 percentile RNA rank) was present in 14% of 514 cancers and independently associated with high PD-1 (p = 0.025), PD-L1 (p < 0.0001), and CTLA-4 RNA expression (p < 0.0001) and with patients not having colorectal cancer (p = 0.0009; multivariate analysis)." (PMID 40297627, 2025).